HIF1A (hypoxia inducible factor 1 subunit alpha)
Diseases named in the same sentence as HIF1A in open-access papers (continued):
Sharing a sentence is not in itself a finding about the gene and the disease.
diabetic cardiomyopathy (9 papers, 2014 to 2026). Diabetic cardiomyopathy is a disorder of the heart muscle in people with diabetes. "Our study examines the relationship between the development of diabetic cardiomyopathy and the partial deficiency of HIF1-α caused by the global deletion of Hif1a functional allele." (PMID 24502509, 2014). "We have shown a correlation between heterozygosity for Hif1α and adverse functional, molecular, and cellular changes associated with diabetic cardiomyopathy." (PMID 24502509, 2014). "According to the data obtained with our mouse model, the loss of Hif1a functional allele contributes to the development of diabetic cardiomyopathy." (PMID 24502509, 2014). "Our molecular analysis showed increased levels of Cxadr, Il6st, Pdgfra, and Slc2a1 in the LV of both Wt and Hif1a+/- diabetic hearts which corresponds to the onset of pathological processes associated with cardiac remodeling in diabetic cardiomyopathy." (PMID 24502509, 2014). "We are unable to determine which cell type or which combinations of cell types are contributing to the increased susceptibility of Hif1a+/- mice to diabetic cardiomyopathy." (PMID 24502509, 2014). "The partial deficiency of Hif1a accelerates the progression of diabetic cardiomyopathy by significantly decreasing LV fractional shortening." (PMID 24502509, 2014). "We next investigated whether the Hif1a-deficient sympathetic nervous system affected the progression of diabetic cardiomyopathy." (PMID 37072781, 2023). "The results presented in this study further suggest that genetic variation at the HIF1A locus may also influence the increased risk for diabetic cardiomyopathy." (PMID 24502509, 2014). "We have hypothesized that the partial deficiency of HIF-1α may compromise cardiac responses under diabetic conditions and increase susceptibility to diabetic cardiomyopathy." (PMID 24502509, 2014). "We have hypothesized that the partial deficiency of Hif1a may compromise cardiac responses under diabetic conditions and increase susceptibility to diabetic cardiomyopathy." (PMID 24502509, 2014). "Therefore, we questioned whether the Hif1a-deficient sympathetic nervous system would affect the development of diabetic cardiomyopathy." (PMID 37072781, 2023). "Therefore, we hypothesized that the Hif1a-deficient sympathetic nervous system would accelerate diabetic cardiomyopathy." (PMID 37072781, 2023). "Defective myocardial HIF-1α expression and impaired HIF-1α signaling have been demonstrated in diabetic patients and contribute to diabetic cardiomyopathy." (PMID 37048134, 2023). "For example, the detrimental roles of reduced activation of HIF-1α contributes to the development of diabetic wounds, adverse post-ischemic myocardial remodeling, the acceleration of diabetic cardiomyopathy, and renal injury." (PMID 37072781, 2023). "In this study, we uncovered a previously undescribed protective role of HIF-1α in the sympathetic system over the progression of diabetic cardiomyopathy in genetically modified Hif1aCKO mice." (PMID 37072781, 2023). "In diabetic cardiomyopathy, consistent with the decreased function and stability of HIF-1α, the myocardium loses its ability to use glucose as a metabolic substrate." (PMID 30158902, 2018). "Our research provides a new insight into the potential role of HIF-1α and Hif1a genetic variations in multiple pathways in diabetic cardiomyopathy." (PMID 24502509, 2014). "The aim of this study was to analyze the functional role of HIF-1α in the development of diabetic cardiomyopathy." (PMID 24502509, 2014). "The attenuation of HIF-1α levels observed here suggests that Lir may also decrease cellular hypoxia or increase oxygen sensing, which is relevant to diabetic cardiomyopathy." (PMID 41155741, 2025). "Up to the present time, HIF-1α and VEGF were mainly explored in diabetic retinal injury, diabetic cardiomyopathy, no report has demonstrated the expression of HIF-1α and VEGF in diabetic gastrointestinal mucosa." (PMID 32650726, 2020).
myelodysplastic syndrome (9 papers, 2012 to 2025). A clonal hematopoietic disorder characterized by dysplasia and ineffective hematopoiesis in one or more of the hematopoietic cell lines. "A recent study has reported that lenalidomide, which is approved for the treatment of MM and myelodysplastic syndromes associated with deletion of the long arm of chromosome 5q, inhibited hypoxia-induced endothelial cell cord formation and HIF-1α accumulation." (PMID 22347385, 2012). "It has been reported that the protein level of HIF‐1α in the patients with myelodysplastic syndrome (MDS) upregulated compared with the control group, which was also found to be associated with poor prognosis." (PMID 32533646, 2020). "Recent results suggest that in myelodysplastic syndrome (MDS) patients, iron overload was related to the decrease of hypoxia inducible factor 1-a (HIF1-a)." (PMID 33036384, 2020). "Supporting this perspective, the upregulation of both HIF1α and WT1 has been reported in patients with myelodysplastic syndrome (MDS) or acute leukemia." (PMID 35465313, 2022). "Given the succinate accumulation, we expect that the HIF1α complex will be stabilized, leading to pseudohypoxia phenotypes in cells with elevated PRMT1 expression, akin to those seen in patients with myelodysplastic syndromes (MDS)." (PMID 40801789, 2025).
nasal polyp (9 papers, 2014 to 2025). "The hypoxia‐induced EMT process has been shown to contribute to nasal polyposis in CRSwNP, mediated by HIF‐1α and phosphorylated Smad3 (pSmad3), leading to a loss of E‐cadherin and induction of α‐SMA." (PMID 40176272, 2025). "EGCG treatment restores the physiological levels of Hif1-α as has been described elsewhere in tissues such as skin and nasal polyp fibroblasts." (PMID 37237934, 2023). "HIF-1α plays a role in the pathogenesis of nasal polyps by regulating the expression of downstream factors, increasing vascular permeability and tissue edema, and promoting the transformation of epithelial cells into mesenchymal cells." (PMID 35075349, 2022). "The CRSwNP group showed significantly elevated MPO activity, PI3K, p-AKT protein, HIF-1α, and IL-17A mRNA levels in nasal polyps." (PMID 35075349, 2022). "Here, we measured both the protein levels and the levels of mRNA encoding of HIF-1α, PI3K, and Akt in nasal polyps." (PMID 35075349, 2022). "HIF-1α is significantly increased in polyp tissues, which promotes neutrophilic inflammation in chronic rhinosinusitis with nasal polyps patients." (PMID 34465337, 2021). "Increased expression of HIF1α and its downstream mediators regulate VEGF protein levels in nasal polyps (NPs)compared with normal turbinate tissue;however, the roles of HIF1α and HIF2α in the pathogenesis of CRSwNP have yet to be elucidated." (PMID 29254228, 2017). "It was previously reported that EGCG suppressed HIF-1α expression in human skin and nasal polyp fibroblasts." (PMID 24558360, 2014). "Furthermore, SEB may be involved in the expression of RORC and HIF-1α in Tregs and by maintaining the inflammation in sinonasal mucosa that could have a main role in the pathogenesis of nasal polyposis." (PMID 35264183, 2022). "Furthermore, SEB may be involved in the higher expression of RORC and HIF-1α in Tregs, and maintaining the inflammation in sinonasal mucosa could lead to nasal polyposis' pathogenesis." (PMID 35264183, 2022). "We found that HIF-1α mRNA levels were significantly higher in nasal polyp groups than in controls, but HIF-1α protein levels were not." (PMID 35075349, 2022). "The protein levels of HIF-1α, p-Akt, and PI3K in nasal polyps were measured via WB." (PMID 35075349, 2022). "However, we found no significant increase in HIF-1α levels in nasal polyps, unlike a previous work." (PMID 35075349, 2022).
polycythemia (9 papers, 2017 to 2026). Abnormally high mass or concentration of red blood cells in the blood, either due to an increase in erythropoiesis or a decrease in plasma volume. "Hepatic Hif2a deficiency corrected erythropoietin expression and polycythemia and attenuated aberrant hepatic gene expression in Slc30a10-deficient mice, while hepatic Hif1a deficiency had no discernible impact." (PMID 38652538, 2024). "The observation that hepatic Hif2a deficiency attenuates Epo excess and polycythemia in Slc30a10–/– mice is consistent with a previous study showing that hepatic Epo expression is regulated by Hif2a, not Hif1a." (PMID 38652538, 2024). "Systemic stabilization of HIF-1α leads to erythropoiesis and angiogenesis and may lead to polycythemia." (PMID 33519819, 2020). "The mechanism underlying hypoxia-induced morphological changes in the microstructure of gastric tissues and the role of HIF-1A in the pathogenesis of high-altitude polycythemia (HAPC) in Tibetans remain unclear." (PMID 31001558, 2019). "Constitutive activation of HIF-1α via VHL deletion or the combined inactivation of PHD1, PHD2, and PHD3 leads to polycythemia and excessive bone accumulation." (PMID 35118061, 2021). "Additionally, axitinib can induce polycythemia and other RBC dysfunction in patients with ccRCC due to complex interactions between hypoxia inducible factor 1 alpha (HIF-1a), VEGF and EPO." (PMID 33602288, 2021).
prostate (9 papers, 2012 to 2025). "The transcriptional activity of HIF-1 complex is determined by the expression of the HIF-1α subunit, which is over-expressed in preneoplastic prostate lesions and has emerged as an important transcription factor in prostate carcinogenesis." (PMID 33920379, 2021). "The reason for this was unknown; although, a strong correlation was identified between NANOG and HIF-1α expression, which may suggest that NANOG and HIF-1α co-operate in prostate carcinogenesis." (PMID 25120646, 2014). "Consistently, SENP1 transgenic mice exhibit an induction of HIF1α with the initial onset of PIN (or low-grade PIN) at 4 months of age, suggesting that SENP1 regulation of HIF1α occurs early in prostate pathogenesis." (PMID 24970135, 2012). "While the specific role of ATF3 (activating transcription factor 3) in the suppression of PCa with PTEN (phosphatase and tensin homolog) dysfunction is meanwhile well known, the tumor suppressor function of IGF1, CXCL10, HIF1A, CXCL8, and CSF1 in prostate carcinogenesis remains to be elucidated." (PMID 36321189, 2023).
prostate adenocarcinoma (9 papers, 2012 to 2024). "Specifically, ONECUT2 activates SMAD3, which regulates hypoxia signaling through moderating HIF-1α transcriptional binding, causing higher degrees of hypoxia in NEPC compared to prostate adenocarcinomas." (PMID 32509575, 2020). "Another study demonstrated that in high-grade prostate adenocarcinomas, 46% of them showed higher nuclear HIF1α immunostaining, and 89% expressed higher levels of VEGF." (PMID 25896712, 2015). "Depletion of PRKAR2B, ADCK2, TRPM7 and TRIB2 significantly decreased HIF-1α accumulation in LNCaP, an androgen-sensitive human prostate adenocarcinoma cell line with low invasive potential." (PMID 22355351, 2012). "Specifically, ONECUT2 activates SMAD3, which regulates hypoxia signaling through modulating HIF1α chromatin-binding, leading NEPC to exhibit higher degrees of hypoxia compared to prostate adenocarcinomas." (PMID 30655535, 2019).
subarachnoid hemorrhage (9 papers, 2008 to 2026). A serious neurological disorder characterized by intracranial hemorrhage into the subarachnoid space. "It has been reported that activation of the HIF-1α/VEGF signaling pathway can alleviate retinal complications caused by subarachnoid hemorrhage." (PMID 39102510, 2024). "In one of these studies, 24 h after subarachnoid hemorrhage, exposure to argon was found to increase HIF1α and HO-1 levels, which reached control levels after 72 h and were a factor that reduced neuronal death." (PMID 39684384, 2024). "This study aimed to investigate the molecular mechanism of how melatonin (MT) interferes with hypoxia-inducible factor 1α (HIF1A) and toll-like receptor 4 (TLR4) expression, which is implicated in the management of delayed brain injury (DBI) after subarachnoid hemorrhage (SAH)." (PMID 35170388, 2022). "However, in a study evaluating the role of HIF-1α in BBB permeability in a rat subarachnoid hemorrhage model, the elevated expression of HIF-1α in brain tissues temporally coincided with brain edema formation and BBB disruption." (PMID 25741233, 2015). "In addition, the preservation of BBB, the reduction in HIF-1α levels, and decreased apoptosis and neuronal damage were observed in a rat model for subarachnoid hemorrhage after exposure to HBO." (PMID 18769544, 2008).
uveal melanoma (9 papers, 2014 to 2022). A melanoma derived from melanocytes of the uveal tract. "VEGF, a transcriptional target of HIF-1α, has also been associated with aggressive behaviour in uveal melanoma." (PMID 25166211, 2014). "In order to prove the importance of HIF-1α protein in the regulation of growth and invasion in uveal melanoma cells, we also performed loss-of-function studies." (PMID 25166211, 2014). "In order to determine downstream targets of HIF-1α responsible for these profound effects on cellular invasion, we examined the expression of Notch pathway members, which we have previously linked to the spread of uveal melanoma cells." (PMID 25166211, 2014). "Treatment with 80 μM cordycepin decreased protein interaction between Hsp90 and HIF-1α in 92.1 uveal melanoma cells, and combination treatment with 10 μM cordycepin and 1 μM EHNA also prominently reduced binding of these proteins." (PMID 35804893, 2022). "After uveal melanoma cells were exposed to hypoxia, the expression and nuclear localization of HIF-1α increased, targeting VEGF genes, including VEGF-A, for its transcription." (PMID 34476217, 2021). "The overexpression of HIF-1α was detected in biopsies derived from patients suffering from skin cancer and uveal melanoma." (PMID 33918883, 2021). "Elevated expression of VEGF and HIF-1α in correlation with vascularity in uveal melanoma patients was also observed." (PMID 33918883, 2021). "We also examined HIF-1α expression in five primary uveal melanoma specimens, which showed some irregular cracking due to artefacts related to freezing and sectioning." (PMID 25166211, 2014). "Mel285 cells have the lowest baseline level of HIF-1α compared to the other uveal melanoma lines, therefore we used this line for additional gain-of-function studies." (PMID 25166211, 2014). "In summary, we demonstrate that HIF-1α is expressed in both normoxic and hypoxic uveal melanoma cell lines, as well as in primary tumor regions rich in blood vessels." (PMID 25166211, 2014). "Although HIF1a is known to be expressed in uveal melanoma (UM), it is as yet unknown which factors, such as tumour size or genetics, determine its expression." (PMID 31323773, 2019). "Thus HIF-1α protein expression is relatively elevated in many uveal melanoma lines under normoxic conditions, but its protein levels and transciptional activity are further induced when oxygen levels are lowered." (PMID 25166211, 2014). "The mTOR inhibitor rapamycin was able to reduce both S6 phosphorylation and HIF-1α protein levels in normoxic tumor cells, suggesting that in uveal melanoma an active mTOR cascade may promote a “hypoxic” transcriptional response even in the presence of oxygen." (PMID 25166211, 2014). "HIF-1α protein is highly expressed in metastatic uveal melanomas." (PMID 25166211, 2014). "Our findings support the functional importance of HIF-1α signaling in promoting the invasive capacity of uveal melanoma cells in both hypoxia and normoxia, and suggest that pharmacologically targeting HIF-1α pathway directly or through blockade of Notch or Erk1-2 pathways can slow tumor spread." (PMID 25166211, 2014). "We examined the effects of oxygen level and HIF-1α expression on the growth and invasion of uveal melanoma cells in order to determine how the hypoxic response might modulate the biology of these tumors." (PMID 25166211, 2014). "Interestingly, we observed that HIF-1α protein is stabilized even in normoxia in most of the uveal melanoma lines examined, broadening the type of microenvironment where targeting HIF would be effective." (PMID 25166211, 2014). "Gene expression analysis of primary uveal melanomas has revealed a number of pathways potentially responsible for the metastatic spread, including the hypoxic signaling mediated by hypoxia-inducible factor 1α (HIF-1α) and its targets." (PMID 25166211, 2014). "We therefore investigated whether this might account for the robust HIF-1α levels noted in normoxic uveal melanoma cells." (PMID 25166211, 2014).
uveal melanoma (continued). "We found expression of hypoxia-inducible factor 1α (HIF-1α) protein in well-vascularized tumor regions as well as in four cell lines grown in normoxia, thus this pathway may be important even in well-oxygenated uveal melanoma cells." (PMID 25166211, 2014). "HIF-1α, Akt, ERK, and EGFR protein levels all decreased in uveal melanoma cell lines after combination treatment." (PMID 35804893, 2022). "Treatment with the mTOR inhibitor rapamycin reduced HIF-1α protein levels in normal oxygen tension in OMM1 and 92.1 cells, supporting a similar paradigm in uveal melanoma cells." (PMID 25166211, 2014). "HIF-1α protein was relatively abundant in the OCM1, OMM1, Mel290 and 92.1 uveal melanoma lines grown in normoxia, and was further induced by up to 5 fold in hypoxia." (PMID 25166211, 2014). "Growth in hypoxia significantly increased cellular invasion of all 5 uveal melanoma lines tested, as did the introduction of an oxygen-insensitive HIF-1α mutant into Mel285 cells with low HIF-1α baseline levels." (PMID 25166211, 2014). "To explore the role of HIF-1α in uveal melanoma, we first determined the baseline expression of HIF proteins and the mRNA levels of their downstream targets VEGF and LOX in uveal melanoma lines grown for 24 hours in normoxia (21% pO2) or hypoxia (1% pO2)." (PMID 25166211, 2014). "In addition, HIF-1α protein stabilization and the increased expression of its target gene, VEGF, was evident in uveal melanoma cells through a mTOR-dependent mechanism, and was shown to promote the invasive capacity of uveal melanoma cells through the AKT signaling pathway." (PMID 34199959, 2021). "Consistent with the role of Hsp90 in promoting HIF-1α and Akt stability, 80 μM and 160 μM cordycepin treatment significantly decreased protein levels of HIF-1α, Akt, ERK, and EGFR in ADA-low (92.1, MM28, Omm1) uveal melanoma cell lines, but not in those with high ADA (MP46 and MP38)." (PMID 35804893, 2022).